BCL2 (BCL2 apoptosis regulator)
Diseases named in the same sentence as BCL2 in open-access papers (continued):
Sharing a sentence is not in itself a finding about the gene and the disease.
hematological malignancies (continued). "Venetoclax, an orally-administered medication that selectively targets the BCL-2 protein, has shown promise in enhancing treatment sensitivity in some hematological malignancies by reducing the apoptotic threshold." (PMID 37071328, 2023). "Venetoclax is a selective oral inhibitor of BCL‐2 which plays an important role in the treatment of hematological malignancies." (PMID 36619491, 2023). "Alterations in these microRNAs expression and in Bcl-2 regulation were already described in human hematological malignancies and new therapeutically approaches focus on that axis." (PMID 36879336, 2023). "Venetoclax, a highly selective BCL-2 inhibitor, has exhibited robust antitumor capacity in hematologic malignancies." (PMID 37894324, 2023). "In these hematological malignancies, the Bcl-2 family alterations have been pointed out as new therapeutic possibilities, with the use of selective Bcl-2 inhibitors such as venetoclax, among others." (PMID 37720343, 2023). "Venetoclax is a selective B-cell lymphoma 2 (BCL-2) inhibitor currently used as monotherapy or in combination with other agents in a wide range of hematologic malignancies, including CLL, myelodysplastic syndrome, and acute myeloid leukemia." (PMID 37760453, 2023). "Venetoclax (or ABT-199) is an inhibitor of the anti-apoptotic protein BCL-2 and has recently been shown to be effective in several hematological malignancies." (PMID 36672458, 2023). "Bcl-2 inhibitors have proven their effectiveness in treating hematological malignancies through multiple preclinical and clinical studies for many years now." (PMID 36639602, 2023). "In the treatment of hematological malignancies, the aim to integrate the application of Bcl‐2 inhibitors has led to further research and development of Bcl‐2 selective and dual Bcl‐2 and Bcl‐xL inhibitors." (PMID 37229486, 2023). "This inhibition of pro-survival BCL-2 results in mitochondrial-mediated apoptosis in BCL-2-dependent hematologic malignancies." (PMID 37760453, 2023). "The high pro-apoptotic efficacy of MCL-1 and BCL-2/BCL-XL co-inhibition was also found in previous studies concerning hematological malignancies and solid tumors." (PMID 37108344, 2023). "The field of BCL-2 inhibitors for hematologic malignancies has seen tremendous progress in recent years, which has raised concerns regarding expanding their applications to solid tumors." (PMID 37894324, 2023). "MCL-1 plays a vital role in the development of hematological malignancies and high expression of MCL-1 is associated with BCL-2 inhibitor resistance." (PMID 35794605, 2022). "Bcl-2 is one of the most important anti-apoptotic proteins in hematological malignancies, which can inhibit the recruitment of BAX and BAK, and block the activation of apoptotic pathway by binding pro-apoptotic proteins." (PMID 36477747, 2022). "Venetoclax, a selective inhibitor of B-cell lymphoma 2 (BCL-2), is a small molecule that has been studied in several hematologic malignancies as both monotherapy and in combination with other agents." (PMID 35198449, 2022). "The therapeutic potential of targeting anti-apoptotics like BCL2 and MCL1 in hematologic malignancies is extensively reviewed in and we have reported on the intersection of cellular metabolism and BCL-2 proteins in." (PMID 36185202, 2022). "Bcl-2 is a miRNA-34a target, thus the reduced expression of miRNA-34a in various solid and hematological malignancies is often accompanied by an increase in Bcl-2 expression." (PMID 35056993, 2022). "The BCL-2 inhibitor venetoclax is currently approved for treatment of hematologic diseases and is widely used either as monotherapy or in combination strategies." (PMID 36313732, 2022). "APG-2575 (lisaftoclax) is a BCL-2 selective inhibitor independently developed by Suzhou Ascentage Pharma, several clinical trials have been initiated in hematologic malignancies." (PMID 35794605, 2022).
hematological malignancies (continued). "In the last years, the B cell lymphoma 2 (Bcl-2) inhibitor Venetoclax (VEN) has emerged as an important therapeutic option in many hematologic malignancies." (PMID 36644527, 2022). "When both BCL-XL and BCL-2 proteins are expressed at similar levels, as evidenced mainly in hematological malignancies, then both proteins can regulate BAX activation." (PMID 35256598, 2022). "Venetoclax, a Bcl-2 inhibitor is currently used for hematological malignancies or is undergoing clinical trials for either hematological or solid tumors." (PMID 35265218, 2022). "Remarkable clinical success with the Bcl-2 inhibitor venetoclax has revolutionized the treatment of hematological malignancies, including AML6,53." (PMID 34707185, 2021). "The combination of ABT-737 with chemotherapeutic agents or other targeted therapy molecules has synergistic efficacy and is a promising molecule for treating BCL-2 dependent solid tumors and hematologic malignancies." (PMID 34638998, 2021). "Unfortunately, despite the biologic rationale and efficacy demonstrated by BCL2 inhibition in other hematological malignancies, our preliminary experience showed that venetoclax monotherapy had therapeutic activity in only 18% of patients, with one case of CR." (PMID 34938664, 2021). "LOXO-338 is another BCL-2 inhibitor being tested in a phase 1 study in advanced hematologic malignancies (NCT05024045)." (PMID 35127532, 2021). "Venetoclax, a small molecule inhibitor of the B-cell lymphoma 2 (BCL-2) antiapoptotic protein, is another novel targeted therapy that has seen broad applications in patients with hematological malignancies." (PMID 34947040, 2021). "BCL-2-targeting BH3 mimetics alone have shown promising activity in hematological malignancies, but they have been mostly ineffective for solid tumors." (PMID 34675185, 2021). "Venetoclax is an anti-BCL2 inhibitor that targets the BH3 domain of BCL2, induces apoptosis in leukemic cells, and is widely used for the treatment of different hematological malignancies." (PMID 33804056, 2021). "Anti-apoptotic proteins, particularly BCL-2, are promising therapeutic targets in hematologic malignancies." (PMID 34198580, 2021). "Some of these pathways have been identified in hematological malignancies, whereby Cer mediates its apoptotic effects via its inhibitory action on Bcl-2 phosphorylation." (PMID 33048123, 2020). "In particular, Bcl-2 and A1 members have antiapoptotic roles and represent important targets of NF-κB in lymphocyte development and hematological malignancies." (PMID 32346377, 2020). "In the last five years, the BH3 mimetic, ABT-199 (venetoclax, a potent small molecule inhibitor against BCL2) has proven to be highly effective for treating advanced hematological malignancies." (PMID 32764384, 2020). "Because BCL-2 inhibitor venetoclax is the only agent that has already been approved for the treatment of patients with hematologic malignancies, we will focus only on mechanisms of sensitivity/resistance to BCL-2 inhibition by venetoclax." (PMID 32290241, 2020). "Oblimersen is an 18-antisense oligonucleotide complementary to the first six codons of BCL-2 mRNA that was evaluated in a variety of hematological malignancies." (PMID 32131385, 2020). "In this regard, the selective inhibitor of the pro-survival protein BCL2, venetoclax, has proven highly effective in several hematological malignancies." (PMID 32913182, 2020). "Venetoclax, an oral BCL-2 inhibitor and the prototype for this class of drugs, has shown promising efficacy in the treatment of several hematologic malignancies." (PMID 30972300, 2019). "Targeted inhibition of the anti-apoptotic Bcl-2 proteins has been shown to have impressive efficacy in the treatment of several hematologic malignancies, with current FDA approvals of venetoclax for the treatment of CLL and AML." (PMID 30972300, 2019).
hematological malignancies (continued). "Another mitocan, ABT-199, which targets the apoptotic inhbitor BCL-2, has shown activity in hematological malignancies, both alone and with other drugs." (PMID 31409768, 2019). "The success story of BCL-2 inhibitors in hematologic malignancies is quite encouraging, along with new MCL1 and IAP inhibitors that are actively being tested in the clinic." (PMID 31370269, 2019). "Venetoclax is a potent and selective inhibitor of the BCL-2 protein that has demonstrated clinical efficacy in several hematological malignancies." (PMID 29747654, 2018). "Importance of Bcl-2 with respect to hematologic malignancies is indirectly documented by the fact that targeting of Bcl-2, by ABT-199, but not Bcl-XL is associated with promising clinical results in CLL and AML." (PMID 29515335, 2018). "Here, we review the role of BCL-2 protein on apoptosis regulation, its importance as therapeutic target for hematological malignancies and the results obtained with BH3-mimetics drugs on preclinical and clinical trials." (PMID 29747654, 2018). "Other models show promise of combining ruxolitinib with a BCL-2 inhibitor; venetoclax is currently in clinical trials to treat additional hematological malignancies beyond CLL, either as a monotherapy or in combination with other chemotherapeutic agents." (PMID 29854301, 2018). "Abnormally high levels of Bcl-2 help sustain tumors and can be used as a target in an approach to treat various hematologic malignancies." (PMID 29531548, 2017). "Venetoclax acts as a direct inhibitor of Bcl-2 and has shown significant activity in a variety of Bcl2-dependent hematologic malignancies." (PMID 27471867, 2016). "The opportunity to induce apoptosis by selectively targeting Bcl-2 with ABT-199 is a potentially promising therapeutic approach in hematological malignancies." (PMID 25797245, 2015). "In hematologic malignancies, BCL2 impairs cell apoptosis by overexpression of the pro-survival protein Bcl2." (PMID 26325180, 2015). "Accordingly, efforts have lately been focused on the development of drugs targeting Bcl-2 proteins with considerable therapeutic success, particularly in hematologic malignancies." (PMID 24603326, 2014). "The Bcl2 inhibitor venetoclax in combination with the hypomethylating agents azacitidine (ven/aza) has become increasingly utilized clinically for the treatment of many hematological malignancies." (PMID 41610429, 2026). "Taken together, several selective BCL2 targeting BH3-mimetics are emerging clinically that may compete with venetoclax for the treatment of hematological malignancies." (PMID 40113751, 2025). "Hence, the expression status of Bcl-2 is a key antiapoptotic protein in various disease conditions, including solid tumors and hematological malignancies." (PMID 38169388, 2024). "We emphasized their important role in the development and maintenance of the immune response and proposed that the combination of BCL-2 inhibitors with immunotherapy may be one of the most promising treatment methods for hematologic malignancies." (PMID 39060763, 2024). "We emphasize their important role in regulating the immune system and propose that the combination of BCL-2 inhibitors with immunotherapy may be one of the most promising treatment methods for hematologic malignancies." (PMID 39060763, 2024). "Regarding hematologic malignancies, the anti-apoptotic molecules Bcl-2 and Mcl-1 are commonly highly expressed, playing a pivotal role in their biological characteristics via the dysregulation of their expression or by being associated with the cell-of-origin of the hematologic neoplasm." (PMID 38610812, 2024). "The current progress of the BCL-2 inhibitor venetoclax in hematologic malignancies." (PMID 37894324, 2023).
hematological malignancies (continued). "On the other hand, a review study focused on the importance of BcL-2 for modulation of apoptosis at the mitochondrial level, its potential as a therapeutic target for hematological malignancies, and the results obtained with selective inhibitors of BH3-mimetics." (PMID 37909594, 2023). "Indeed, multiple such agents have been demonstrated to synergistically interact with Bcl-2 inhibitors in various hematologic malignancies." (PMID 35574302, 2022). "In this review, we outlined the most important steps in the development of targeting the BCL-2 survival proteins, which laid the ground for the discovery and the development of the selective BCL-2 inhibitor venetoclax as a therapeutic drug in hematological malignancies." (PMID 33799470, 2021). "In fact, numerous preliminary clinical studies have demonstrated that venetoclax, an oral potent BCL2 antagonist approved to treat multiple hematological malignancies, plus standard-of-care regimens yield a survival benefit for BCL2-overexpressed DLBCL patients." (PMID 33777762, 2021). "Indeed, Efforts to develop targeted BCL-2 therapy in hematologic malignancies have been longstanding." (PMID 34198580, 2021). "Interestingly, the guaianolides were able to inhibit cell viability in U-937/Bcl-2, a subline that overexpresses the survival protein Bcl-2, which has been involved in chemoresistance, especially in hematologic malignancies." (PMID 33371413, 2020). "Moreover, AZD0466, a dual Bcl-2/Bcl-xL inhibitor is under clinical evaluation in hematologic malignancies and advanced solid tumors (NCT04214093)." (PMID 32455818, 2020). "The therapeutic strategy of targeting anti-apoptotic BCL-2 proteins has been clinically validated by the FDA approval of venetoclax for the treatment of various hematologic malignancies including CLL and SLL as a single agent, and for AML in combination with low-intensity chemotherapy." (PMID 34296214, 2020). "Thus far, the limited success seen in other hematological malignancies and solid tumors only serves to underscore the following challenges we face in harnessing the benefit of BCL-2 inhibitors more broadly." (PMID 32131385, 2020). "B-cell Lymphoma 2 (BCL-2) homology domain 3 (BH3)-mimetics are emerging as a novel class of apoptosis-inducing agents that are currently being tested for the treatment of different hematological malignancies including AML." (PMID 31801941, 2019). "Moreover, reports showing MCL-1 and BCL-2 co-inhibition is tolerated in mice, and is synergistic in hematological malignancies, are starting to emerge." (PMID 31019203, 2019). "Therefore, selective BCL2 inhibitors, such as venetoclax, which has been shown to be effective against hematological malignancies 45, might be an option for targeted treatment, particularly for patients with BCL2A1-positive PSCC." (PMID 33391539, 2021). "BCL2 is an attractive target in DLBCL, and the specific BCL2 inhibitor venetoclax is clinically used for multiple hematological malignancies." (PMID 40819126, 2025). "The effects of CDK9 have been studied in hematologic malignancies, and many of them have suggested the downregulation of master transcription factor MYC or upregulation of anti-apoptotic molecules such as MCL1 and BCL2." (PMID 40713627, 2025). "The first BCL2-selective BH3-mimetic, venetoclax, showed remarkable efficacy with manageable toxicities and has transformed the treatment of several hematologic malignancies." (PMID 40113751, 2025). "A phase Ib study is currently investigating the use of the BCL-2 inhibitor VOB560 and the MCL1 inhibitor MIK665 in hematological malignancies, to examine their safety and dosage (NCT04702425)." (PMID 39906657, 2024). "Nevertheless, the role of the Akt signaling pathway possibly by upregulation of non-Bcl-2 antiapoptotic proteins such as MCL-1 and Bcl-XL in the development of venetoclax resistance has been confirmed in hematologic malignancies." (PMID 39035053, 2024).
hematological malignancies (continued). "ABT-199, the first specific Bcl-2 inhibitor, was approved by FDA for the treatment of several hematological malignancies." (PMID 37460459, 2023). "In hematological malignancies, compared with the normal group, patients with DLBCL had high expression of BCL‐2 and VEGFR‐2." (PMID 36053810, 2022). "Venetoclax is an effective and selective BCL-2 inhibitor that disrupts BCL-2 signaling and induces apoptosis in hematological malignancies." (PMID 36032118, 2022). "Small molecule inhibitors targeting cellular oncoproteins and enzymes such as BCR-ABL, JAK2, Bruton tyrosine kinase, FLT3, BCL-2, IDH1, IDH2, are biomarker-driven chemotherapy-free agents approved for several major hematological malignancies." (PMID 33879198, 2021). "The development of BH3 mimetics allowed for effective targeting of anti-apoptotic proteins in tumors that are dependent on BCL-2 or BCL-XL and opened up a new avenue for targeted therapeutics in hematologic malignancies." (PMID 30972300, 2019). "Venetoclax, also known as ABT-199, is a selective BCL2 protein inhibitor approved by the FDA for the treatment of chronic lymphocytic leukemia as monotherapy therapy, and in combination therapies for other hematologic malignancies." (PMID 39836700, 2025). "Although BCL-2 is one of the main anti-apoptotic proteins, especially in hematological malignancies, immunoblotting analyses did not reveal the presence of this protein (data not shown)." (PMID 40113795, 2025). "After outlining the research and development process, drug resistance, and safety of BCL-2 inhibitors above, we review the current application status of BCL-2 inhibitors in various hematologic malignancies and their combined efficacy with immunotherapy to improve their efficacy." (PMID 39060763, 2024). "A switch of the apoptotic dependency from BCL-2 to other anti-apoptotic proteins, such as MCL-1 or BCL-XL, or even a general reduction of apoptotic priming has been described in venetoclax resistance in several hematological malignancies." (PMID 36672458, 2023). "In several studies, the anti-apoptotic BCL2 protein was overexpressed in MCS; therefore, BCL2 inhibitors, e.g., Venetoclax used in hematological malignancies treatment, may be a promising target in MCS treatment." (PMID 37760551, 2023). "ABT-263 (Navitoclax), which targets BCL-2, BCL-XL, and BCL-W, is FDA approved as well for combination therapy in hematological malignancies and is being studied in multiple clinical trials for several solid tumors (ClinicalTrials.gov Identifier: NCT02591095; NCT00878449; NCT00891605)." (PMID 33917026, 2021). "However, there has been some success in this area using relatively large small molecules such as the first in class BCL-2 inhibitor venetoclax, which recently gained FDA approval for use in patients with a number of hematological malignancies." (PMID 31408950, 2019). "Prior research by others suggests that STAT5 knockdown triggers apoptosis through anti-apoptotic BCL-2 signaling via the intrinsic pathway in various hematologic malignancies and non-malignant T-cells." (PMID 29682185, 2018). "The impact of new biologicals for hematological malignancies that inhibit B-cell receptor (BCR) signaling pathway, B cell leukemia/lymphoma-2 (Bcl-2) antagonists, and chimeric antigen receptor (CAR) T cells in terms of long-term infectious complications has not been established." (PMID 27597852, 2016). "Since BCL-2 plays a major role as an anti-apoptotic protein in multiple hematological malignancies, ABT-199 has the potential to be effective as a single agent or in combination with other agents toward a broad spectrum of hematological malignancies." (PMID 26589495, 2015). "BCL-2 and BCL-XL are antiapoptotic members of the BCL-2 family that modulate cell death in an autophagy-independent manner and are overexpressed in several hematological malignancies." (PMID 25328887, 2014).